PVR (PVR cell adhesion molecule)
Diseases named in the same sentence as PVR in open-access papers (continued):
Sharing a sentence is not in itself a finding about the gene and the disease.
tumor (continued). "CD155, or PVR, is involved in many cellular processes, e.g., cell adhesion and tumour immune escape, but it can also result in immune activation by binding its receptor DNAM1 on NK cells; thus, it is of great interest for immunotherapy." (PMID 34209558, 2021). "This evidence reveals that the status of FAS and PVR genes may represent a novel biomarker predicting the outcome of NB patients, thus suggesting that their restoration could improve disease status through an immunomodulatory action that could involve NK-cell-mediated innate anti-tumor functions." (PMID 34503178, 2021). "TIGIT binds with high-affinity to CD155 (PVR) and with low-affinity to CD112 (PVRL2; nectin-2) which are expressed in the tumor microenvironment (TME) by antigen presenting cells (APCs) and tumor cells." (PMID 34025646, 2021). "Existing evidence has suggested that PVR can inhibit the function of NK cells via interacting with TIGIT, thereby suppressing the deteriorating effects against tumor cells." (PMID 34150627, 2021). "Nonetheless, efficient tumor cell killing requires additional activating signaling, such as that of DNAM-1 (CD226) interacting Nectin-2 (CD112) and poliovirus receptor (PVR or CD155) ligands." (PMID 34064810, 2021). "In LIHC, the expression of PVR/CD155, PVRL1/CD111, and PVRL2/CD112 was significantly higher in tumor tissues than that in normal tissues." (PMID 33581644, 2021). "Two major ligands for TIGIT are poliovirus receptor (PVR, CD155) and poliovirus receptor-related 2 (PVRL2, CD112, nectin-2), which are expressed by tumor cells as well as myeloid cells." (PMID 33581644, 2021). "TIGIT expression impairs T/NK cells via binding to CD155 (PVR) and CD112 (Nectin2) expressed in myeloid cells and tumor cells." (PMID 33535613, 2021). "PVR binds to TIGIT, which is highly expressed in natural killer cells, T-cells, and regulatory T-cells, and induces immune escape of tumor cells." (PMID 33879814, 2021). "Both HLA class 1/2 and immune checkpoint ligands for TIM-3 (e.g., HMGB) and TIGIT (e.g., PVR and PVRL2) were highly expressed by most tumours." (PMID 34503115, 2021). "Known ligands are PVR (CD155) and Nectin-2 (CD112), which are expressed by a variety of different tumor types." (PMID 34572949, 2021). "In COAD and READ, the expression of PVR/CD155, PVRL1/CD111, PVRL2/CD112, TIGIT, and PVRIG/CD112R was significantly higher in tumor tissues than that in normal tissues." (PMID 33581644, 2021). "PVR, the major ligand of TIGIT, plays a pivotal role in multitudinous biological processes, especially the tumor immune escape." (PMID 34068552, 2021). "We further investigated the anti-tumor effects of azelnidipine in a CT26 model, which is widely used for CD47/SIRPα and TIGIT/PVR blockade therapy and the exploration of the T cell immune response." (PMID 34068552, 2021). "The ligands of DNAM-1 are CD112 (nectin-2, PRR2) and CD155 (PVR, Necl4), which are expressed in some immune cells such as monocytes, DCs, activated CD4+ T cells, and tumor tissue." (PMID 32774149, 2020). "PVR (also known as CD155 or Necl-5) and Nectin-2 (also known as Pvrl2 or CD112) are two major ligands that are expressed on epithelial and myeloid cells of the tumor (Human Cell Atlas,2,3)." (PMID 32489646, 2020). "The known ligands for TIGIT are CD155 [also known as poliovirus receptor (PVR)] and CD112 (also known as nectin-2) that are expressed on myeloid, endothelial or tumor cells." (PMID 33117369, 2020). "Expression of CD112 (nectin-2) and CD155 (poliovirus receptor; PVR), which are NK cell activating ligands, is increased in virus-infected cells and tumor cells." (PMID 33256093, 2020). "TIGIT is expressed on both activated T and NK cells and interacts with two specific DNAM-1 (CD226) ligands, CD155 (PVR) and CD112 (nectin-2), which are expressed on both immune and tumor cells." (PMID 32610578, 2020).
tumor (continued). "Two TIGIT ligands, CD155 (PVR) and CD112 (PVRL2, nectin-2), have been identified; they are primarily expressed on APCs (such as dendritic cells and macrophages) and tumor cells." (PMID 30863404, 2019). "NK cells also express members of the immunoglobulin (Ig) superfamily such as the activating receptor DNAM-I, which has been shown to recognize CD112 (PVR) and CD155 (Nectin-2), two ligands expressed on tumor cells." (PMID 31474977, 2019). "Poliovirus receptor (PVR, also called CD155), a surface receptor highly expressed on DCs, fibroblasts, and some tumor cells, has high-affinity ligation to TIGIT." (PMID 31597242, 2019). "Here, we found that TIGIT and Poliovirus receptor (PVR, CD155) are expressed in tumour cells; the TIGIT and CD155 protein expression in cancer tissue has been found to be significantly higher than that in the precancerous tissue." (PMID 31090213, 2019). "Compared to non-tumor tissues (N), a variety of factors like TGF-β1, TGF-β2, HMGB1, PVR, nectin-2, galectin-9, PD-L1, PD-L2, and MICA/MICB were significantly higher in the tumor tissue (T)." (PMID 31234517, 2019). "Soluble PVR isoforms are generated by alternative splicing and have an inhibitory effect on DNAM-1 mediated tumor immunity." (PMID 31736972, 2019). "The ligands for these two receptors (MICA, MICB and ULBP1-6 for NKG2D receptor and PVR/CD155 and Nectin2/CD122 for DNAM-1 receptor) are expressed on different type of tumor cells and induced by several anticancer drugs." (PMID 31040907, 2019). "Here, we discuss the interactions between PD-1, TIGIT, PVR, CD226, CD96 and CD112 and focus on how they work together to deliver immune stimulatory or inhibitory signals among tumor cells and immune cells within the TME." (PMID 29735917, 2018). "TIGIT ligands belong to the PVR/nectin family, among which PVR (CD155) shows the highest affinity and is commonly expressed on myeloid and upregulated on tumor cells." (PMID 30400822, 2018). "TIGIT is upregulated on tumor antigen-specific CD8+ T cells and CD8+ tumor-infiltrating lymphocytes in various cancer types and TIGIT receptor/poliovirus receptor (PVR) ligand interaction signaling inhibits cytotoxicity mediated by NK and CD8+ T cells." (PMID 30400822, 2018). "Interestingly, except that TIGIT was reported to be expressed on NK and T cells, the expression of PVR was also observed on CD4+ T cells, CD8+ T cells and NK cells, indicating the function of these cells might be suppressed by TIGIT on tumor cells via interaction with PVR." (PMID 30555485, 2018). "Conversely, PVR (CD155), CD112 and CD226 (DNAM-1) are expressed by dendritic cells (DCs), T cells, tumor cells and many other cell types." (PMID 29735917, 2018). "Together, these results provide possibility that tumor cells exert immunosuppressive role on NK and CD8+ T cells through the interaction of tumor-TIGIT and immune cells-PVR." (PMID 30555485, 2018). "DNAM-1 recognizes CD155 (also known as Poliovirus receptor or PVR) and CD112 (Nectin-2) on tumor cells and induces NK cell-mediated lysis." (PMID 28955340, 2017). "TIGIT has two ligands, namely, CD155 (poliovirus receptor, PVR) and CD112 (PVRL2) that are expressed on APC as well as on tumor cells." (PMID 29276510, 2017). "TIGIT binds two ligands, CD112 (PVRL2, nectin-2) and CD155 (PVR), and these ligands are expressed by T cells, APCs, and tumor cells." (PMID 28545567, 2017). "CD112 (Nectin-2, PVRL2) and CD155 (Necl5, PVR) bind CD226 (DNAM-1), which potentiates in vitro the cytotoxicity of NK cells against a wide range of tumor cells; CD58 (LFA-3) binds CD2 and its co-engagement with ICAM-1 increases NK response." (PMID 26106390, 2015). "DNAM-1 is a co-receptor expressed by virtually all NK cells and its stimulation by interaction with the members of the nectin family, PVR (CD155) and Nectin-2 (CD112), on tumor cells leads to NK cell activation and target cell lysis." (PMID 25889680, 2015).
tumor (continued). "Tumor cells utilize various mechanisms to evade immune system surveillance, including the expression of checkpoint proteins such as PD-L1, CTLA-4, Galectin-9, and PVR." (PMID 41550509, 2026). "ADAR-mediated RNA editing may enhance tumor- and immune-related gene activities and pathways in CRC by upregulating PVR expression." (PMID 39126156, 2025). "Finally, we analysed the expression of those genes in our GeoMx data, which revealed decreased levels of almost all genes, bar PVR, VSIR and NECTIN2, in the primary tumour, compared to healthy tissues." (PMID 41168392, 2025). "Additionally, γδT cells express DNAM-1 (CD226), which binds to CD155 (PVR) and CD112 (Nectin-2), further strengthening tumor recognition and immune activation." (PMID 40226616, 2025). "Furthermore, these cells interacted with tumor cells via TGF-β and NOTCH signaling pathways, contributing to ECM remodeling, while also suppressing immune responses through the PVR-TIGIT signaling axis." (PMID 40107247, 2025). "Additionally, PVR (CD155) suppressed T-cell function by interacting with the DNAM-1 receptor, further promoting T-cell exhaustion and immune suppression in the tumor microenvironment." (PMID 40529377, 2025). "Elevated TIGIT expression may contribute to an immunosuppressive tumor microenvironment by interacting with its ligands (e.g., PVR, NECTIN-2) expressed by stromal and malignant cells, thereby promoting T cell exhaustion and enabling tumor immune evasion." (PMID 40799645, 2025). "It binds to its ligands CD155 (PVR) or NECTIN-2 (CD112), which are frequently overexpressed on malignant or antigen-presenting cells (APCs), TIGIT suppresses cytotoxic immune responses, contributing to immune evasion within the tumor microenvironment (TME)." (PMID 40799645, 2025). "To examine this possibility, we collected a confirmed list of immunosuppressive genes and found a positive correlation between p62 and the main suppressors of T-cell immune function on the tumor cell surface, including EBAG9, PVR, B7-H3, TNFRSF14, TGFB1, and PD-L1, in most cancers." (PMID 41291343, 2025). "Indeed, the top 30 significantly enriched immune modulators in ME patients included CCL8, a ligand for the tumour infiltrating Treg cells chemokine receptor CCR8, PVR, a ligand for the T cell checkpoint protein TIGIT and ITGA8, which is known to activate TGFb." (PMID 39915477, 2025). "In this study, mice receiving PTSO-pretreated hPBMCs exhibited significantly reduced PVR gene expression within the tumor, suggesting that PTSO may contribute to tumor immunogenicity by reversing immune suppression mediated by this pathway." (PMID 41010517, 2025). "Hence, we assessed the tumor cell expression of four distinct immune checkpoint ligands; PD-L1, CD80, GAL-9, and PVR, which interact with the clinically relevant receptors PD-1, CTLA-4, TIM3, and TIGIT on T cells." (PMID 40108668, 2025). "In this report, PVR expression did not correlate with tumor-infiltrating lymphocytes, whereas PD-L1 was highly expressed on tumor-associated macrophages and positively correlated with TILs, indicating that PVR and PD-L1 have different expression patterns." (PMID 39156900, 2024). "TIGIT, DNAM1, and CD96 (TACTILE) are known receptors for PVR in the immune system; binding of PVR to TIGIT suppresses tumor immunity while binding to DNAM1 promotes tumor immunity; binding to CD96 acts both to suppress and promote tumor immunity." (PMID 39156900, 2024). "However, most reports on PVRL2 and PVR in the immune system focus on the interaction of PVRL2 and PVR expressed in tumor cells with T and NK cells." (PMID 39156900, 2024). "Additionally, CTL tumor cells also displayed TIGIT expression after recurrence, resulting in a heightened interaction between TIGIT on tumor cells and CD155/PVR on monocytes." (PMID 38464517, 2024). "Furthermore, in the TCGA cohorts, PVR and PVRL2 were significantly upregulated in HCC tumour compared to non tumour liver samples." (PMID 37383234, 2023).
tumor (continued). "TIGIT could be engaged with the two ligands, CD155 (PVR) and CD112 (PVRL2, Nectin-2), expressed by tumor cells and antigen-presenting cells in the tumor microenvironment." (PMID 38203670, 2023). "Moreover, using immunohistochemistry (IHC) data from the Human Protein Atlas database, we demonstrated significant upregulation of PVR and PVRL2 in HCC tumour compared to normal liver samples." (PMID 37383234, 2023). "In addition, TIGIT has been found to bind three ligands, namely CD155 (PVR), CD112 (PVRL2, nectin-2), and CD113 (PVRL3), which are expressed by tumor cells, antigen-presenting cells, and also T-lymphocytes in the tumor microenvironment." (PMID 36765782, 2023). "In addition to PDL1, EBVaGCs express higher levels of CD155/PVR, CEACAM1, and galectin-9 mRNAs, which represent known anti-tumor immunity genes that antagonize T cell responses." (PMID 36680216, 2023). "Vδ2+ T cells are activated by cells that accumulate HMBPP and/or IPP and can also be stimulated through receptors NKG2D and DNAM-1 of various stress-induced molecules expressed on tumor cells including MICA/B, UL16-binding proteins (ULBP1–6), Nectin-2, and PVR, respectively." (PMID 36851283, 2023). "Notably, a recent study found that the intercellular communications between PVR+ malignant cells and CD226+ T cells can enhance the anti-tumor immune response." (PMID 37859818, 2023). "TIGIT competes with CD226 to bind to PVR (CD155) and Nectin-2 (CD112) two molecules often up-regulated on tumor cells thus playing an important role in the NK-cell activity inhibition in part counterbalanced by the co-stimulatory activity exert by DNAM-1(CD226) receptor." (PMID 36291830, 2022). "Importantly, the depletion of PVR/CD155 reduced the speed of migration, proliferation and tissue invasion of the tumor cells." (PMID 36568222, 2022). "We hereby show that L-XRT can downregulate PVR expression on antigen-presenting cells (APCs), and the combination of RadScopal + anti-TIGIT + anti-PD1 may yield favorable local and systemic tumor control." (PMID 35008385, 2022). "PVR expression was not correlated with age (with either the 40- or 58-year old threshold), tumor size, lymph node status, or PD-1 expression." (PMID 36544779, 2022). "TIGIT is mainly expressed on the surface of activated T cells and NK cells, and its receptors are primarily poliovirus receptors (PVR, CD155) and VR-like protein 2 (PVRL2, CD122), which are highly expressed in tumor cells and APCs, and are newly discovered immune checkpoint ligands." (PMID 35892835, 2022). "Furthermore, KIR2DL5-mediated inhibition on NK cytotoxicity was abolished upon depletion of PVR on tumor cells, corroborating that KIR2DL5 acts via PVR." (PMID 36377656, 2022). "Besides, cytokines such as PVR and NECTIN2 also participate in building the tumor immunosuppressive microenvironment." (PMID 36685571, 2022). "Levels of PVR are usually low (or PVR is not expressed) in normal tissues, but are high in tumor cells." (PMID 33879814, 2021). "By targeting PVR, azelnidipine could significantly restrict the CT26 tumor growth at both administration dosages." (PMID 34068552, 2021). "TIGIT binds to its ligand PVR or CD155 on the tumour cells with a much higher affinity than its activating counterpart CD226 (DNAM-1), thereby inhibiting the interaction between CD226 and CD155 which is widely expressed on tumour cells." (PMID 33995362, 2021). "Interestingly, we saw that in tissue-derived exosomes, PVR was downregulated in exosomes by NAC, suggesting that tissue-derived exosomes become less tumour-promoting after NAC." (PMID 34209558, 2021). "We found that tumor-infiltrating CD33high cells showed high gene expression levels of CD36, CD14, FUT4 (CD15), CD80, CD86, CSF1R and immune checkpoint ligand genes including CD274 (PD-L1), LGALS9 (galectin-9), PVR and VSIR." (PMID 33000418, 2021).
tumor (continued). "TIGIT can interact with poliovirus receptor (PVR, CD155) on DCs to induce IL-10 secretion for suppressing the Th1 T-cell response, inhibiting the NF-κB pathway and preventing the effective cytotoxic immune response, which is required to reject the tumour." (PMID 34445385, 2021). "In fact, above induction of the pro-survival and proliferation gene, MYC controls the expression of different immune checkpoint proteins on the tumor cell surface, such as the innate immune regulator, CD47 (cluster of differentiation 47), and NK-activating ligands, such as MICA/B and PVR." (PMID 34503175, 2021). "In addition, we recently discovered that Poliovirus receptor (PVR), one of the checkpoint TIGIT ligands, is expressed by tumor epithelial cells." (PMID 34290984, 2021). "A blockade of receptor–ligand interaction by targeting TIGIT or PVR could reverse the exhaustion of NK and CD8+ T cells and enhance the anti-tumor immunity." (PMID 34068552, 2021). "Given their expression of PVR, TNFRSF14 and CD80/CD86, they might be under direct control by TIGIT+CTLA4+CSF2+TNFSF14+ tumor cells." (PMID 33968070, 2021). "Since that the TIGIT/PVR immune checkpoint axis plays a major role in the functional regulation of T cells and NK cells, we also explored the role of CD4+, CD8+ T and NK cells in the tumor inhibition mediated by liothyronine therapy." (PMID 32894141, 2020). "PVR is relatively absent in normal tissues, but regularly overexpressed in malignancies promoting tumor cell invasion and migration." (PMID 32506804, 2020). "It has been reported that aspirin could inhibit tumor cell growth by reducing the expression level of TIGIT, and that emodin could elicit the anti-tumor effects through downregulating the expression of PVR." (PMID 32894141, 2020). "The role of DNAM-1 ligands in tumor cell recognition and killing by NK cells is actually more complex, since, besides DNAM-1, also the inhibitory receptors CD96 and TIGIT can recognize PVR or PVR and Nectin-2, respectively." (PMID 31316503, 2019). "Two of these ligands, Necl-5 (usually termed CD155 or PVR) and Nectin-2 (CD112), frequently expressed on different types of tumor cells, are recognized by a group of receptors expressed on T and NK cells that exert opposite functions after interacting with their ligands." (PMID 31234588, 2019). "Our findings elucidated that tumor-intrinsic TIGIT could help the tumor to grow by suppressing the function of NK and CD8+ T cells, which can be restored by TIGIT antibody or PVR blockade." (PMID 30555485, 2018). "PVR recognition by CD226 potentiates CD8 T cell and NK cell cytotoxicity toward tumor cells." (PMID 26347741, 2015). "With the aim to increase the visibility of tumor cells to NK cells, three bispecific immunoligands carrying a HER2-specific scFv and the ECD of B7-H6, AICL or PVR were generated to trigger NK cells via the activating receptors NKp30, NKp80 or DNAM-1, respectively." (PMID 26392331, 2015). "K562 tumor cells express ligands for receptors promoting natural cytotoxicity (Nectin-2/PVR for DNAM-1; MICA/B/UBLP1 for NKG2D), but do not express the 2B4 ligand CD48 or classical HLA-A, B, C, and non-classical HLA-E." (PMID 23508354, 2013). "Similar to NKG2D, sustained engagement of DNAM‐1 with PVR on tumor cells leads to downregulation of DNAM‐1 on the NK cell surface, potentially through receptor internalization followed by proteasomal degradation or by shedding of PVR from the tumor cell membrane into the extracellular environment." (PMID 40959206, 2025). "PVR/TIGIT, NECTIN2/CD226, and FAM3C/PDCD1 were relatively more strongly expressed in Plac1+ epi‐CD4+ T cells than Plac1− epi‐CD4+ T cells and PVR was specific for Plac1+ tumor cells, which was subsequently validated in HNSCC cells in vitro and in the TMA cohort by mIF." (PMID 40056047, 2025).